HIF1A (hypoxia inducible factor 1 subunit alpha)
Diseases named in the same sentence as HIF1A in open-access papers (continued):
Sharing a sentence is not in itself a finding about the gene and the disease.
cancer (continued). "This study suggested that HIF-1α is a major determinant for cancer cell homeostasis under cytotoxic stress, and targeting aerobic glycolysis and HIF-1α may be a useful and specific strategy for chemotherapy." (PMID 24658058, 2014). "Our results suggest that the inhibition of HIF-1α expression may sensitize the IMQ-induced apoptosis in cancer cells." (PMID 24658058, 2014). "From these results, we speculated that HIF-1α may enhance cancer mortality by promoting distant metastasis." (PMID 25377659, 2014). "Metformin is a potential anti-cancer agent targeting the mTOR/HIF-1α pathway." (PMID 25310259, 2014). "Certain miRNAs and HIF-1α confer drug resistance or sensitivity to cancer cells." (PMID 25531114, 2014). "In recent years, the HIF-1α gene has been a research focus in the scientific community, and many epidemiological studies have been performed to assess the association between HIF-1α C1772T/G1790A polymorphisms and cancer susceptibility." (PMID 25496056, 2014). "First, we demonstrated that the inhibition of HIF-1α expression by RNAi strategy may sensitize the IMQ-induced apoptosis in cancer cells." (PMID 24658058, 2014). "Hypoxia-inducible factor-1α (HIF-1α) is a transcriptional master regulator that enhances various metastatic mechanisms (e.g., cell survival, angiogenesis, and invasion) by hypoxia 29 and is upregulated by hypoxia in cancer cells 30,31." (PMID 24634093, 2014). "Over-expression of HIF-1α has been reported in many types of cancer, including lung, prostate, breast, colon and rectum carcinoma, and in regional or distant metastases, implying that it may play a vital role in tumor progression." (PMID 24808762, 2014). "In contrast, the association results of SNP 1772 C > T of HIF-1α gene with different kinds of cancers were not consistent in literature review." (PMID 25302049, 2014). "Thus, small-molecule HIF-1α inhibitors from natural products have potential as molecularly targeted cancer therapeutics." (PMID 25105148, 2014). "Since it is overexpressed in many cancer, HiF-1α became a target for anti-cancer therapies." (PMID 25338163, 2014). "Interestingly, suppression of HIF1α by treatment with antioxidants has been shown to inhibit cancer cell proliferation in vitro and in vivo." (PMID 25671107, 2014). "It has been reported that HIF-1α may be a key factor for determining cancer malignancy and prognosis." (PMID 25120692, 2014). "Together, these results suggest that the specific and higher uptake and accumulation of NIR dye by canine and human cancer tissues could be mediated by hypoxia-induced HIF-1α and specific OATPs." (PMID 25361418, 2014). "HIF-1α expression was observed in the nucleus of cancer cells." (PMID 23558457, 2014). "HIF-1α induces the expression of hundreds of target genes; those regulating angiogenesis and glucose metabolism are some of the most important with respect to cancer growth." (PMID 25421331, 2014). "Some anti-cancer drugs increase cancer cells radiosensitivity by downregulating HIF-1α." (PMID 24886405, 2014). "Our model leads to the hypothesis that the pVHL/HiF-1α complex formation rate is divided by about 100 in this type of cancer." (PMID 25338163, 2014). "In addition, under normoxic conditions, the expression and activity of HIF-1α and the subsequent secreted angiogenic factors in cancer can be abnormally up-regulated by different signaling pathways involving Akt and its downstream effectors." (PMID 25162518, 2014). "However, the available data on the relationship between HIF-1α and the chemoresistance of cancer cells are conflicting." (PMID 24901645, 2014). "HIF-1α is frequently deregulated in cancer and correlates with poor patient prognosis." (PMID 25355043, 2014).
cancer (continued). "To understand the roles played by HIFs in cancer phenotype maintenance and their possible interaction with canonical Wnt signaling, we examined the effects of the stable knockdown of HIF-1α and HIF-2α by siRNA in SW480 cells, which exhibit constitutively active canonical Wnt signaling." (PMID 25396735, 2014). "The transcriptional factor HIF-1α, one of the key regulators of oxygen homeostasis, is an important mediator of solid tumor development in vivo because it promotes angiogenesis and inhibits cancer apoptosis." (PMID 24988190, 2014). "We explored whether the blockade of HIF-1α or HIF-2α expression in cancer cells that express both factors under normoxia also affects cellular survival." (PMID 25396735, 2014). "Likewise, exposure to hypoxic conditions reduce the levels and the extent of drug-induced senescence in cancer cells, in a HIF-1α dependent manner." (PMID 24984035, 2014). "Moreover, HIF-1α activates transcription of genes that play key roles in critical aspects of cancer biology, including stem cell maintenance (NOTCH1, WNT-β catenin pathways), angiogenesis (VEGF, iNOS signalling) and metastasis." (PMID 24732040, 2014). "Nuclear HIF-1α was considered positive in 104/315 (33%) carcinomas." (PMID 25269858, 2014). "In addition to these ECM and related components and EMT markers, HIF1α, an important microenviromental factor linking mitochondrial dysfunction with cancer tumorigenesis and metastasis, was also increased under normoxic conditions." (PMID 23630608, 2013). "Furthermore, the HIF-1α inhibitor 2-methoxy estradiol (2-ME) significantly reduced in vitro metastatic properties, suggesting the possibility for drug treatment to reduce cancer invasion and metastasis." (PMID 24216696, 2013). "Moreover, previous studies demonstrated a link between β-adrenoceptors and HIF-1α in several cancer cells, indicating an up-regulation of HIF-1α by catecholamine-mediated β-adrenoceptor stimulation also under normoxic conditions." (PMID 23596415, 2013). "Further studies should be performed to explore the potential functional role of HIF-1α in malignant tumors and to determine whether HIF-1α may be regarded as an indicator or target in the diagnosis and treatment of TSCC." (PMID 23251251, 2013). "However, angiogenesis is stimulated by significantly increased VEGF levels, activated HIF-1α and NFκB pathways in cancer." (PMID 23638734, 2013). "However, no previous studies have investigated the correlation between Annexin A3 and HIF-1α expression in types of human cancer." (PMID 24260057, 2013). "Whereas the trend from these studies is that HIF1α and HIF2α promote cancer progression, the association is not absolute." (PMID 24216979, 2013). "Nonetheless, our in vitro data support the hypothesis that a strong metabolic impairment impacts on the HIF-1α-dependent adaptive ability of cancer cells, likely via a TCA imbalance." (PMID 24280190, 2013). "A previous study demonstrated that HIF-1α is involved in the development of drug resistance in several types of cancer, however, its role in paclitaxel sensitivity in the A2780 cell line remains unclear." (PMID 24137413, 2013). "On the other hand, HDACIs have been shown to induce autophagy and attenuate HIF-1α in cancer cells." (PMID 24312289, 2013). "As recently reported, these changes may contribute to HIF-1α dependent protection of Ewing cells from anti-cancer drug- or tumor necrosis factor-related apoptosis-inducing ligand (TRAIL)-induced apoptosis." (PMID 24391834, 2013). "The overexpression of HIF-1α in BRCA carrier cancers has been described elsewhere." (PMID 23326384, 2013). "By detecting the Ki67 label index, VEGF, HIF-1α and numerous other molecules that are significant in cancer progression and metastasis, it has also been demonstrated that the overexpression of LAT1 is correlated with cell proliferation, angiogenesis and hypoxia." (PMID 23946786, 2013).
cancer (continued). "However, once cancer cells acquire HIF-1α expression, they transform to more aggressive and metastatic behavior." (PMID 23799043, 2013). "In agreement with the present findings, metabolic control by V600EBRAF could be envisaged on the basis of its signaling through the MEK and ERK kinases and activation of MYC or HIF-1α, both of which are major determinants of cancer metabolism." (PMID 23603840, 2013). "HDAC4 regulates hypoxia-inducible factor 1 α (HIF1 α) and cancer cell response to hypoxia." (PMID 23819581, 2013). "Epigenetic regulation of HIF-1α has been evaluated in cell culture and cancer models." (PMID 23559860, 2013). "However, MEL has not been reported to have an anti-angiogenesis effect through HIF-1α protein decrease in cancer cells." (PMID 23936001, 2013). "HIF1α may also be involved with oncogenic alterations to glucose metabolism because it activates cancer-related gene transcription and affects pathways such as angiogenesis, cell survival, glucose metabolism, and cell invasion." (PMID 23718763, 2013). "The current study identifies an important link between PI3K/AKT and HIF-1α, which may have particular relevance to disease progression as well as therapeutic target for cancer intervention in RMS and ES." (PMID 23590596, 2013). "Furthermore, the HIF-1α expression outcome was stronger in all familial groups than in sporadic cancers (p = 0.0045)." (PMID 23326384, 2013). "VEGF is an HIF-1α-driven angiogenic factor involved in cancer cell proliferation and invasion." (PMID 23819061, 2013). "Cancer cells undergoing angiogenic switch also produce chemoattractants and mitogens, including HIF1-α (hypoxia-inducible factor 1-alpha), VEGF, FGF-1, CCL2 (C-C motif chemokine 2), and CXCL12 (stromal cell-derived factor 1), for endothelial cells and proangiogenic immune cells." (PMID 23717341, 2013). "In recent years, evidence has started to emerge that HIF-1α activity might also influence the intrinsic invasive behaviour of the cancer cell." (PMID 23740575, 2013). "Previous reports show that HIF-1α activates pyruvate dehydrogenase kinase (PDK)-1 under hypoxic conditions that regulates mitochondrial oxygen consumption in cancer cells by inhibiting pyruvate dehydrogenase, the enzyme responsible for converting pyruvate into acetyl CoA." (PMID 23840849, 2013). "HIF-1α downregulation may inhibit proliferation, induce apoptosis, and enhance radiosensitivity in hypoxic cancer cells." (PMID 23618526, 2013). "While increased expression/activity of transcription factors HIF-1α and c-myc is thought to play an important role in the increased glycolysis in cancer cells, the underlying mechanisms are not completely understood." (PMID 23866118, 2013). "FCF reduced HIF-1α protein expression levels in most of the tested cancer cells." (PMID 23977378, 2013). "Overexpression of HIF-1α has been reported in other cancers and may result from degradation-insensitive forms of this protein or increases in mTOR activity." (PMID 23460817, 2013). "A novel autocrine loop (IL-6/STAT3/HIF-1α) that operates in cancer cells was recently discovered." (PMID 24314323, 2013). "Several studies suggest that HIF-1α regulates expression of VEGF in cancer cells." (PMID 23123638, 2013). "We examined several cancer cell lines for HIF-1α accumulation under TNFα treatment." (PMID 22355351, 2012). "In cancer cells, high glucose induces the accumulation of hypoxia inducible factor (HIF)-1α and the associated expression of VEGF; however, in normal cells, such exposure to high glucose inhibits HIF-1α and VEGF expression." (PMID 22853690, 2012). "We compared the amounts of HIF-1α in several cancer cell lines, and found that U251 cells had relatively low expression levels under normoxic conditions (data not shown); this indicated that factors other than hypoxia were less effective at inducing HIF-1α in U251 cells." (PMID 22211243, 2012). "HIF-1α is an important factor that plays a role in cancer progression." (PMID 23243443, 2012).
cancer (continued). "Similarly, plasminogen activator inhibitor-1 (PAI-1), a factor related to the uPAR system that predicts poor prognosis in many cancers, is regulated by hypoxia through the cooperative functions of HIF-1α, Egr-1, and C/EBPα." (PMID 23241400, 2012). "Furthermore, downregulation of HIF-1α by siRNA increased the sensitivity of cancer cells to chemotherapies and irradiation." (PMID 22211243, 2012). "mTOR was found to be an upstream activator of HIF-1α expression in cancer cells." (PMID 22992293, 2012). "On the other hand, cancer cells in perinecrotic/pimonidazole-positive regions are under low glucose conditions, less than 0.45 g/L (2.49 mM), resulting in a decreased level of HIF-1α even under hypoxic conditions." (PMID 23203043, 2012). "Furthermore, clinical data shows that increased levels of HIF-1α and HIF-2α are associated with higher patient mortality in many human cancers." (PMID 22454562, 2012). "Because HIF-1 promotes both glycolytic energy production and angiogenesis, it is not surprising that increased levels of HIF-1α are associated with poor cancer prognosis." (PMID 22428047, 2012). "The transcription factor HIF1α is one of the central players of cancer-specific aerobic glycolysis." (PMID 22481926, 2012). "HIF-1α is a main regulator of the transcriptional response of cancer cells to hypoxia." (PMID 22357313, 2012). "In addition, the transcription factors, HIF1-α and NF-κB, play crucial roles in various processes, such as inflammation, microbial killing and cancer progression." (PMID 22479608, 2012). "Furthermore, our results suggest that four of these genes - ADCK2, PRKAR2B, TRIB2 and TRPM7 - seem to regulate HIF-1α accumulation in multiple cancer cell lines." (PMID 22355351, 2012). "HIF-1α becomes resistant to both chemotherapy and radiotherapy in cancers under hypoxia." (PMID 23243443, 2012). "HIF1α is responsible for the majority of the hypoxia response in cancer." (PMID 22852079, 2012). "To date, HIF1α is known as a key regulator of hypoxic response in many cancers." (PMID 22970168, 2012). "The role of HIF1α has been well documented in cancers originating in the ovary." (PMID 22481926, 2012). "Thus, it is imperative while developing HIF-1α inhibitors as anti-cancer agents to evaluate their effects on cell cycle and cell death." (PMID 23028659, 2012). "HIF-1α pathway exists as a critical step in carcinogenesis, which was implied by a growing body of evidence due to its linkage to several oncogenic and tumor suppressor gene pathways in cancer." (PMID 22952803, 2012). "The HIF-1α gene is believed to activate the production of numerous angiogenic growth factors, and has various effects on cancer, regulating at least 70 genes, most of which promote cancer." (PMID 23181101, 2012). "Moreover, we had simply thought that cancer cells stained with pimonidazole in perinecrotic regions would show high HIF-1α expression." (PMID 23203043, 2012). "Moreover, cumulative evidence has shown that suppression of VEGF and HIF-1α inhibited carcinoma cell proliferation." (PMID 22615958, 2012). "In addition, in vivo animal and in vitro cell culture studies showed that HIF-1α activation was induced by NF-κB in various cancer cells, including lung cancer cells, colon cancer cells, and osteosarcoma cells." (PMID 21119667, 2011). "Moreover, hypoxic incubation of cancer stem cells isolated from GBM revealed that HIF-1α and NF-kB have different time courses of activation within the first 24 h." (PMID 21489226, 2011). "Interestingly, the time courses of activation of pro-inflammatory proteins analyzed in hypoxic cancer stem cells were similar to that of HIF-1α, with an increase after 6 h and a decrease after 24 h." (PMID 21489226, 2011). "This approach could be useful to indirectly control stress-induced glucocorticoid responses, or in cancer therapeutics, provide a novel mechanism to control HIF-1α activity." (PMID 21526215, 2011).
cancer (continued). "PHD2 is primarily responsible for regulating basal HIF-1α levels in cancer cells." (PMID 21709315, 2011). "Thus, recently STAT3 and HIF-1α are attractive target molecules by natural compounds and herbal extracts in cancer research." (PMID 21731766, 2011). "Moreover, inhibition of PDK1 expression has been shown to decrease lactate levels and HIF-1α expression and reduce the malignant phenotype of cancer cells." (PMID 21541279, 2011). "However, some scholars have suggested that the effect of HIF-1α overexpression depends on the cancer type." (PMID 21843314, 2011). "HIF-1α activation is a common feature of tumors; it is generally more pronounced in aggressive tumors and can be an independent predictor of poor prognosis in certain types of cancer." (PMID 21843314, 2011). "Further findings indicate that more than co-acting in cancer stem cell maintenance, hypoxia could drive the maintenance of a cancer stem cell niche, with a strong participation of HIF-1α." (PMID 21824412, 2011). "The lead compound, LS081, facilitated iron uptake which resulted in reduced cancer cell growth, colony formation, and decreased HIF-1α and -2α protein levels, suggests that this class of compounds could be a useful anti-cancer agent." (PMID 21453502, 2011). "We demonstrate that clear cell cancer cell lines survive better than serous cell lines under hypoxia and glucose deprived conditions and this is in part due to these activated pathways involving HIF1 α and enolase." (PMID 21754983, 2011). "Although it was shown that HIF-1α inhibition reduced angiogenesis and tumour growth in xenografted gastric tumours, it has become evident that the mechanism underlying the activation of HIF-1 in various cancer cells depends on cancer type." (PMID 21119667, 2011). "Due to the importance of HIF-1α in cancer, targeting HIF-1α could become a novel approach in cancer therapy." (PMID 21085474, 2010). "Thus tumoral HIF-1α inhibition is becoming an increasingly attractive therapeutic target in the treatment of cancer." (PMID 20398289, 2010). "Furthermore, inhibition of HIF-1α by means of RNA interference or pharmacological compounds has proven antitumoral efficacy in various murine cancer models." (PMID 20706634, 2010). "Our data suggest that agents inhibiting both HIF-1α and HIF-2α, or their target genes, may likely be effective in treating cancers with oncogenic KRAS mutations." (PMID 21073737, 2010). "THL dose-dependently inhibited the hypoxia-induced HIF-1α expression in MDA-MB-231 cancer cells." (PMID 20429953, 2010). "HIF-1α has emerged as an attractive target for cancer therapy." (PMID 21143841, 2010). "Our findings suggest that 1, 9 PA is a lead compound of a novel class of drugs that may be used to enhance the response of cancer cells to cetuximab through a complementary effect on the downregulation of HIF-1α." (PMID 21209911, 2010). "Since Se is part of the mammalian physiology, it is relatively well tolerated and affects multiple upstream targets such as HIF-1α, Cox-2, and iNos important for cancer survival and progression and is likely to have a better success as an antiangiogenic agent in combination chemotherapy." (PMID 20445750, 2010). "A possible mechanism for this increase could be inhibition of hypoxia-mediated activation of extracellular signal-regulated kinase 1/2 and Akt, leading to a marked decrease in HIF-1α, as reported to occur in Resveratrol treated cancer cells." (PMID 21113404, 2010). "Besides its inhibitory effect on endothelial cells, THL inhibited hypoxia-induced HIF-1α and vascular endothelial growth factor-A expression in cancer cells." (PMID 20429953, 2010). "To date, regulation of cancer glucose metabolism has been predominantly linked to HIF-1α rather than HIF-2α." (PMID 21073737, 2010). "Firstly, we found that THL could inhibit the hypoxia-induced expression of HIF-1α which is a transcriptional activator of the vegf-A gene, in cancer cells." (PMID 20429953, 2010).